RMDN2 (regulator of microtubule dynamics 2)
Synonyms: RMD-2; FAM82A; FAM82A1; BLOCK18; FLJ32954; RMD2; PRO34163; PYST9371; RMD4
Tractability: Antibody: UniProt predicts a signal peptide or a membrane-spanning region. PROTAC: ubiquitination databases record sites on it; its protein half-life has been measured.
Gene: Protein-coding gene on chromosome 2 (37,923,187 to 38,067,142, forward strand). Ensembl gene ENSG00000115841.
Subcellular location: Membrane; Cytoplasm; Cytoplasm, cytoskeleton, spindle; Cytoplasm, cytoskeleton, spindle pole
Subcellular location (Human Protein Atlas): Cytosol; Mitotic spindle; Golgi apparatus
Gene Ontology:
Molecular function: microtubule binding; protein binding
Cellular component: cytosol; mitochondrion; mitotic spindle; mitotic spindle pole; spindle microtubule; cytoplasm; membrane; spindle; spindle pole
Genetic constraint (gnomAD): Loss-of-function variants: 18 observed, 16.76 expected, observed/expected ratio (o/e) 1.07, 90% interval 0.74 to 1.59. The upper end of that interval is the gene's LOEUF score, 1.59, which puts it in group 6 of 6, group 1 being the genes least tolerant of losing a copy. Missense variants: 310 observed, 263.05 expected, observed/expected ratio (o/e) 1.18, 90% interval 1.07 to 1.29. Synonymous variants: 99 observed, 91.45 expected, observed/expected ratio (o/e) 1.08, 90% interval 0.92 to 1.28.
Homologues: Orthologues: guinea pig RMDN2 (83% identical), mouse Rmdn2 (80% identical), rat Rmdn2 (60% identical), tropical clawed frog rmdn2 (48% identical), Caenorhabditis elegans rmd-2 (22% identical), zebrafish rmdn2 (19% identical), Caenorhabditis elegans C16C8.18 (16% identical), Caenorhabditis elegans rmd-6 (15% identical), Caenorhabditis elegans sup-35 (15% identical), Caenorhabditis elegans rmd-3 (14% identical), Caenorhabditis elegans rmd-1 (13% identical). Paralogues in human: RMDN3 (36% identical), RMDN1 (21% identical), TEX10 (18% identical).
Diseases named in the same sentence as RMDN2 in open-access papers:
RMDN2 is named in the same sentence as 3 diseases in open-access papers, as found by Europe PMC text mining. Sharing a sentence is not in itself a finding about the gene and the disease. The quoted sentences say what the papers report.
lung carcinoma (1 paper, 2023). "We noted that RMDN2, as the parent gene of rno-Rmdn2_0006, could regulate microtubule dynamics proteins, and research has shown that RMDN2 is associated with the pathogenesis of lung cancer." (PMID 37153858, 2023).
malignant melanoma (1 paper, 2020). "A genome-wide association analysis suggested a potential relationship between the RMDN2 3’UTR and increased susceptibility to malignant melanoma." (PMID 31487369, 2020).
RMDN2 also shares sentences with these, for which no sentence is quoted: experimental autoimmune encephalomyelitis (1 paper).